PSENEN (presenilin enhancer, gamma-secretase subunit)
Description:
Essential subunit of the gamma-secretase complex, an endoprotease complex that catalyzes the intramembrane cleavage of integral membrane proteins such as Notch receptors and APP (amyloid-beta precursor protein). The gamma-secretase complex plays a role in Notch and Wnt signaling cascades and regulation of downstream processes via its role in processing key regulatory proteins, and by regulating cytosolic CTNNB1 levels (Probable). PSENEN modulates both endoproteolysis of presenilin and gamma-secretase activity. Besides its role in gamma-secretase complex, acts as a regulator of AMP-activated protein kinase (AMPK) activity in response to calorie restriction: binds metformin, an antidiabetic drug, promoting association with ATP6AP1, a subunit of the V-ATPase complex, leading to V-ATPase complex inhibition on lysosomes and AMPK activation via the AXIN1-STK11/LKB1 axis (By similarity).
Synonyms: PEN2; MDS033; ACNINV2; MSTP064; PEN-2
Tractability: Small molecule: a drug acting on it is in phase 2 or 3 trials; a structure with a bound ligand is known; a high-quality ligand is known; it belongs to a druggable protein family. Antibody: UniProt places it where antibodies can reach, with high confidence; its Gene Ontology location is reachable by antibodies, with high confidence; UniProt predicts a signal peptide or a membrane-spanning region. PROTAC: ubiquitination databases record sites on it; a small molecule that binds it is known.
Target class: Enzyme
Gene: Protein-coding gene on chromosome 19 (35,745,070 to 35,747,519, forward strand). Ensembl gene ENSG00000205155.
Subcellular location: Endoplasmic reticulum membrane; Golgi apparatus, Golgi stack membrane; Cell membrane; Membrane
Pathways (Reactome):
Signal Transduction: Activated NOTCH1 Transmits Signal to the Nucleus; NOTCH2 Activation and Transmission of Signal to the Nucleus; NOTCH3 Activation and Transmission of Signal to the Nucleus; NOTCH4 Activation and Transmission of Signal to the Nucleus; NRIF signals cell death from the nucleus; Noncanonical activation of NOTCH3; Nuclear signaling by ERBB4; Regulated proteolysis of p75NTR; TGFBR3 PTM regulation
Disease: Constitutive Signaling by NOTCH1 HD+PEST Domain Mutants; Constitutive Signaling by NOTCH1 PEST Domain Mutants
Developmental Biology: EPH-ephrin mediated repulsion of cells
Metabolism of proteins: Amyloid fiber formation
Gene Ontology:
Molecular function: endopeptidase activator activity; enzyme binding; protein binding; molecular function inhibitor activity
Biological process: amyloid precursor protein catabolic process; amyloid precursor protein metabolic process; amyloid-beta formation; membrane protein ectodomain proteolysis; membrane protein intracellular domain proteolysis; positive regulation of endopeptidase activity; protein processing; cellular response to glucose starvation; negative regulation of TORC1 signaling; Notch receptor processing
Cellular component: endoplasmic reticulum; endoplasmic reticulum membrane; gamma-secretase complex; Golgi apparatus; membrane; plasma membrane; endosome membrane; Golgi membrane; Golgi cisterna membrane; presynaptic membrane
Genetic constraint (gnomAD): Loss-of-function variants: 4 observed, 16.59 expected, observed/expected ratio (o/e) 0.24, 90% interval 0.12 to 0.55. The upper end of that interval is the gene's LOEUF score, 0.55, which puts it in group 2 of 6, group 1 being the genes least tolerant of losing a copy. Missense variants: 112 observed, 127.03 expected, observed/expected ratio (o/e) 0.88, 90% interval 0.76 to 1.03. Synonymous variants: 42 observed, 49.49 expected, observed/expected ratio (o/e) 0.85, 90% interval 0.66 to 1.1.
Homologues: Orthologues: chimpanzee PSENEN (100% identical), macaque PSENEN (100% identical), dog PSENEN (99% identical), guinea pig PSENEN (99% identical), pig PSENEN (98% identical), rabbit PSENEN (98% identical), mouse Psenen (96% identical), rat Psenen (96% identical), zebrafish psenen (76% identical), tropical clawed frog psenen (71% identical), Drosophila melanogaster pen-2 (60% identical), Caenorhabditis elegans pen-2 (43% identical).
Diseases named in the same sentence as PSENEN in open-access papers:
PSENEN is named in the same sentence as 25 diseases in open-access papers, as found by Europe PMC text mining. Sharing a sentence is not in itself a finding about the gene and the disease. The quoted sentences say what the papers report.
Alzheimer disease (10 papers, 2010 to 2024). A progressive, neurodegenerative disease characterized by loss of function and death of nerve cells in several areas of the brain leading to loss of cognitive function such as memory and language. "Seven of these genes are Alzheimer’s disease-related, six are down-regulated with both Apoer2-ICDs (COX7A2L, FZD2, KIF5A, MAP2K2, PSENEN, RAF1) and one with only the Apoer2-ICD[Δ19] (SLC39A9)." (PMID 37461529, 2023). "In CN samples, interestingly, among the most significant pathways enriched with significant CpGs is the KEGG pathway “Alzheimer’s disease”, which was curated based on recent AD literature and included genes that confer AD risks, such as APOE, PSENEN, MAPT, CALM3, MME, and others." (PMID 37038196, 2023).
familial hidradenitis suppurativa (1 paper, 2025). "Additionally, loss of function mutations in PSEN1, PSENEN and NCSTN all cause familial hidradenitis suppurativa, a chronic inflammatory skin condition, further supporting a putative anti-inflammatory role of γ-secretase." (PMID 40542358, 2025).
glioma (1 paper, 2019). A benign or malignant brain and spinal cord tumor that arises from glial cells (astrocytes, oligodendrocytes, ependymal cells).
Huntington disease (1 paper, 2014). Huntington disease (HD) is a rare neurodegenerative disorder of the central nervous system characterized by unwanted choreatic movements, behavioral and psychiatric disturbances and dementia. "The third group is composed of proteins involved in oxidative phosphorylation, Alzheimer's and Huntington's diseases (NADH dehydrogenases and PSENEN), antioxidant function and Parkinson's disease (PARK7)." (PMID 24587296, 2014).
PASH syndrome (1 paper, 2024). "Additionally, it is essential to explore why mutations in γ‐secretase complex genes such as NCSTN and PSENEN, known for causing HS, can also lead to PASH syndrome, which encompasses PG and acne." (PMID 38031879, 2024).
cancer (5 papers, 2005 to 2025). A tumor composed of atypical neoplastic, often pleomorphic cells that invade other tissues. "Presenilin enhancer gamma-secretase subunit (PSENEN), the straight target of metformin, is highly expressed in several cancers." (PMID 39624136, 2024). "It was discovered that prognostic risk model-related three genes, including PASK, PSENEN, and RCC2, were upregulated in cancer tissue compared to normal Breast tissue, as shown in." (PMID 40725242, 2025). "Immunohistochemical analyses suggested that PSENEN expression levels in KIRC tumor tissues were markedly higher compared to that in the paracancer tissues, and its expression levels increased continuously with the deterioration of cancer." (PMID 39624136, 2024).
neurodegenerative disease (3 papers, 2016 to 2021). A disorder of the central nervous system characterized by gradual and progressive loss of neural tissue and neurologic function. "Three of the common E2 and NRF1 target genes, GPR37, MAPT, and PSENEN are associated with neurodegenerative disease." (PMID 27983596, 2016). "Three of the genes, GPR37, MAPT and PSENEN observed interacting with all three BPA, E2, and NRF1 are associated with neurodegenerative disease." (PMID 27983596, 2016). "Two of the genes, MAPT and PSENEN, observed interacting with all three EE, E2 and NRF1 are associated with neurodegenerative disease." (PMID 27983596, 2016).
PSENEN also shares sentences with these, for which no sentence is quoted: infection (15 papers); tumor (5); acne inversa (2); breast carcinoma (2); fungal infection (2); aortic stenosis (1); bacterial infections (1); brain disease (1); Dowling-Degos disease (1); familial Alzheimer disease (1); genodermatosis (1); inflammatory skin disease (1); neurological diseases (1); Parkinson disease (1); pulmonary arterial hypertension (1); Senile plaques (1); triple-negative breast carcinoma (1); vitamin D deficiency (1).